IFNG (interferon gamma)
Diseases named in the same sentence as IFNG in open-access papers (continued):
Sharing a sentence is not in itself a finding about the gene and the disease.
influenza (647 papers, 2008 to 2026). An acute viral infection of the respiratory tract, occurring in isolated cases, in epidemics, or in pandemics; it is caused by serologically different strains of viruses (influenzaviruses) designated A, B, and C, has a 3-day incubation period, and usually lasts for 3 to 10 days. "TNF has been associated with potent anti-influenza activity, including increased production of cytokines and chemokines and stronger inhibition of viral replication than IFNγ by lung epithelial cells." (PMID 40476519, 2025). "Influenza infection is a recognized risk factor for pulmonary aspergillosis, as it triggers an early exuberant influenza-induced interferon-gamma (IFN-γ) production." (PMID 40172196, 2025). "On the other hand, IFNγ secretion during severe Influenza infection has been associated with immune-paralysis state in AMs." (PMID 37081878, 2023). "In summary, this study highlights the age-related decline in the IFNγ and iGrB response to influenza challenge which corresponds to the increased risk for serious complications of influenza in older adults." (PMID 35128529, 2021). "The mutation resulted in higher levels of NK cell IFNγ production and significantly higher survival during influenza infection." (PMID 32974217, 2020). "Protection against influenza infection has been associated with various factors, including the presence of influenza-specific serum antibodies, polyfunctional B and T cells, particularly IFNγ-producing CD4+ T cells, memory CD8+ T cells, and CD38+ plasmacytoid dendritic cells (pDCs)." (PMID 40766325, 2025). "We hypothesize that the increased IFNγ levels seen in IL‐6 deficient mice during IAPA may be driven by influenza infection." (PMID 40420617, 2025). "Moreover, mice deficient in IFNγ show decreased immunopathology in response to influenza infection, which is associated with increased IL-5 production by ILC2s, suggesting that ILC2s protect against immunopathology." (PMID 38684766, 2024). "Additionally, an IFNγ-based enzyme-linked immunospot (ELISPOT) assay revealed more IFNγ-expressing cells in the Bst2+/+ DC-vaccinated group than in the Bst2−/− DC-vaccinated group upon stimulation with influenza-infected antigen-presenting cells." (PMID 39796009, 2024). "Influenza infection has also been described to induce IFNγ-dependent AM training with NK cells being the major source." (PMID 40624927, 2025). "We evaluated serum concentrations of seven cytokines (IL-2, IL-4, IL-6, IL-10, TNFα, IFNγ, and IL-17a) as potential biomarkers for influenza severity in pregnant women." (PMID 40558593, 2025). "This supports our previous finding via ELISPOT assay against the influenza antigen, where the N3-treated group produced more IFNγ spots than the L3 groups." (PMID 38543954, 2024). "The preliminary immunogenicity results in mice reported here with a relevant pandemic influenza strain (whole H5N1) showed a significant enhancement of IFNγ expression in CD8+ T cells for formulation with the highest loading of tomatine and SG101." (PMID 40836981, 2024). "As the CD4+ T cell-specific immunodominant LCMVgp61-80 epitope contains a cryptic epitope recognized by CD8+ T cells, we analyzed CD8+CD44+ T cells at 8 and 42 days after influenza challenge for IFNγ expression following LCMVgp61-80 peptide restimulation." (PMID 39283916, 2024). "This suggests an important protective role of IFNγ‐secreting CD4+ T cells in influenza which warrants further investigation in humans." (PMID 38317404, 2024). "GITR expression by lung ILC1s can inhibit IFNγ production in response to influenza infection in mice." (PMID 38684766, 2024). "ILC2s can also convert to IFNγ-producing ILC1s in response to influenza, which potentially contributes to COPD." (PMID 38684766, 2024). "NK cells from vaccinated individuals exhibited increased influenza-specific IFNγ response to influenza antigen upon restimulation in vitro and high cytotoxic response to autologous HBsAg-pulsed monocyte-derived DCs." (PMID 39599860, 2024).
influenza (continued). "IL-27 induces IL-10+ secretion by IFNγ+virus-specific T cells (Tr1-like cells), controlling exacerbated inflammation and conferring host protection from immunopathology in the lung during influenza infection." (PMID 38966644, 2024). "Using mouse models of influenza and lung metastatic tumors, they showed that influenza enhanced the phagocytic and cytotoxic functions of AMs in an IFNγ-dependent manner, leading to lasting resistance to tumor-induced immune suppression." (PMID 37081878, 2023). "We also observed the upregulation of pSTAT3 in the natural killer cell population within human and NHP samples treated with IFNγ compared to human participants challenged with influenza, although overall pSTAT3 expression was higher in the influenza group." (PMID 36624212, 2023). "CD8 T cells are also recruited to the site of the influenza infection and are nearly exclusively IFNγ-producers." (PMID 37696824, 2023). "The data shown here in the low-dose-infected ferrets align with our previous longitudinal assessment of influenza-specific IFNγ responses both in the periphery and in the lung." (PMID 37242338, 2023). "Influenza-specific IFNγ responses in terminal blood showed a trend for infected hamsters to have higher responses at day 4 post-infection to MP1, MP2, HA, NA and NP compared to day 14 post-infection in both young and older hamsters." (PMID 37242338, 2023). "At days 4 and 14 post-infection, whole blood (PBMCs), lung (lung MNCs) and spleen (splenocytes) were collected to assess influenza-specific IFNγ responses." (PMID 37242338, 2023). "Sequential small bleeds allowed for longitudinal influenza-specific IFNγ responses in the ferrets to be monitored over 14 days." (PMID 37242338, 2023). "One example of immunosenescence is the reduced antibody production and cell mediated responses (IFNγ) in geriatric patients following influenza vaccination." (PMID 37699951, 2023). "Together, these data indicate that COVR-M mount a stronger circulating IFNγ and corresponding transcriptional response in both innate and adaptive immune cells by D1 following influenza vaccination." (PMID 35233581, 2022). "IL-27 also has potent antiviral effects against influenza, hepatitis B and C viruses, human immunodeficiency virus and others, by stimulating IFNγ production by CD8+ T cells and modulating innate responses." (PMID 36148243, 2022). "Moreover, decreasing levels of interferon gamma, interleukin 2, and tumor necrosis factor alpha, as well as the activation of the bradykinin 2 receptor signaling pathway, constitute potential mechanisms underlying the stabilization of atherosclerotic plaques by influenza vaccination." (PMID 35665329, 2022). "Specifically, influenza antigens conjugated to both 3 μm and to 500 nm particles induced higher levels of the pro-inflammatory cytokines IFNγ and TNFα in CD4+ T cells than the unconjugated particles." (PMID 35890185, 2022). "Lung homogenates were evaluated by multiplex ELISA (Quansys) to quantify several cytokines (TNFα, IFNγ, IL-1α, IL-1β and IL-6) and chemokines (MCP-1, MIP-1α and RANTES) implicated in influenza-mediated acute lung injury 33,34." (PMID 35410323, 2022). "CD40 L and IFNγ levels were detected after stimulating Tfh cells with an influenza antigen; the positive rates of CD27 and CD38 in B cells were detected before and after coculture with Tfh cells." (PMID 35494526, 2022). "In elderly subjects that developed influenza, IFNγ levels were 10-fold lower from A/H3N2-stimulated PBMCs, and this was a better correlate of poor protection from the subsequent 2003–04 trivalent influenza vaccine than antibody titre." (PMID 36845567, 2021). "The primary comparison planned was between those older adults randomized to the HD vs. SD formulation of seasonal influenza vaccine using our established methods for measuring cytokine (IFNγ, IL-10) and cytolytic T cell (iGrB) responses to vaccination." (PMID 35128529, 2021).
influenza (continued). "Previous randomized trials have measured the CMI response to influenza vaccination in older adults according to changes in IFNγ+, CD4+, or CD8+ T cell frequencies." (PMID 35128529, 2021). "Hemagglutination-inhibition (HAI) titres and IFNγ and IL-10 responses following ex vivo influenza A/H3N2- or B-challenge were measured pre- and post-vaccination and compared between participants who developed LCII and those who did not." (PMID 33430191, 2021). "By contrast, additional studies of influenza vaccines demonstrated that, although IFNγ increased following immunization in all subjects, young subjects produced higher levels than the elderly and that this response correlated with better antibody titres." (PMID 36845567, 2021). "For example, virus-specific cytotoxic T lymphocytes (CTLs) are quickly recruited to influenza-infected lungs by a Th1 response, specifically due to the production of IFNγ Two of these Th1-type effector T-cell chemokine receptors are CXCR3 and CX3CR1." (PMID 34394127, 2021). "The effect of prior season influenza vaccination was decreased iGrB levels, and increased IFNγ and IL-10 levels, which correlated with influenza A/H3N2 hemagglutination inhibition antibody titers." (PMID 35128529, 2021). "In contrast, the anti-inflammatory IL-10 response is better preserved and contributes to an overall decline with aging in the IFNγ:IL-10 ratio in response to ex vivo influenza challenge." (PMID 35128529, 2021). "Immunization via vaccination with influenza-derived peptides provided asthma protection through the interferon-gamma response." (PMID 34721391, 2021). "Total CD4 T cell reactivity at any time point was defined as the total number of cells that produce any of the 4 effector responses (IFNγ, Granzyme B, IL-4 and IL-10) to the different MPs from all 4 influenza strains." (PMID 33922875, 2021). "Previously, enhanced influenza vaccine responses in humans and mice were explained by an increase in IFNγ in serum." (PMID 34025665, 2021). "TRM derived IFNγ is known to be critical for protection against influenza, so these findings support the contribution of the DP population to the antiviral response." (PMID 34566986, 2021). "Virus-specific CTL are quickly recruited to influenza-infected lungs by a Th1 response, specifically due to the production of IFNγ." (PMID 34394127, 2021). "Vaccination with MVA-NP+M1 results in a rapid increase in influenza-specific cross-reactive interferon gamma (IFN-γ)-secreting effector T-cells across age groups, which are maintained at levels above baseline responses over the course of a year." (PMID 34451976, 2021). "Our previous studies suggest that the addition of a toll-like receptor (TLR4) agonist to SVV can overcome the suppressive effects of IL-10 and improve the IFNγ response and markedly improve the IFNγ:IL-10 ratio and GrB response to influenza challenge." (PMID 35128529, 2021). "Although IFNγ-producing T cells have been studied in response to live attenuated and trivalent inactivated influenza vaccines, to our knowledge, the full polarization pattern following Flucelvax immunization has not been fully investigated prior to our study." (PMID 33922875, 2021). "At 0, 4, 10, and 20 weeks post-vaccination, serum antibody titers, IFNγ, IL-10, and inducible GrB (iGrB) were measured in ex vivo influenza-challenged PBMC." (PMID 35128529, 2021). "NK cells produce IFNγ in response to rabies, influenza and DTP vaccinations, with increased levels of NK cell responsiveness observed as much as six months following vaccination." (PMID 32698362, 2020). "Hemagglutination-inhibition assays, antibody to Influenza A virus nucleoprotein and peripheral blood mononuclear cells for measurement of interferon-gamma ELISPOT response to influenza antigens, Granzyme B and IFNγ:IL-10 ratio were measured." (PMID 32698532, 2020).
influenza (continued). "In the lung at 3dpi, highly enriched GO terms included “response to interferon-gamma”, “regulation of NF-kappaB”, “granulocyte chemotaxis” and “response to virus”, which are key influenza responses." (PMID 32050986, 2020). "This is in agreement with a previous study showing increased IFNγ-secretion following seasonal influenza vaccination." (PMID 32517137, 2020). "Depletion of either IFNγ or IL-6 resulted in reduced frequency of influenza-specific antibody secreting cells." (PMID 32698362, 2020). "A recent study in 2019 compared the adult γδTCR repertoire between healthy and influenza-infected adults, revealing that influenza-reactive Vγ9+Vδ2+ T cells exhibit an enrichment of public Vγ9+ clonotypes with IFNγ-production capabilities." (PMID 33255339, 2020). "Here, we demonstrate that the small molecule adjuvants investigated induce significant influenza-specific IFNγ+ T cells and/or IL17 production compared to A/Vic alone." (PMID 32210973, 2020). "Influenza vaccines were reported to induce changes in NK cell receptor repertoires and to promote increased IFNγ secretion." (PMID 32517137, 2020). "In particular, we found that the influenza infection induced in the nasal epithelium early and altered responses in interferon gamma signaling, B-cell signaling, apoptosis, necrosis, smooth muscle proliferation, and metabolic alterations." (PMID 31461941, 2019). "Using the 2017–18 LAIV formulation, a CD4+ IFNγ-positive or CD4+ IL2-positive T-cell response was seen in 55–68% of children to the influenza antigens tested, with approximately 80% of children showing a response to haemagglutinin or matrix and nucleoprotein." (PMID 31235405, 2019). "IP-10 is a well-established IFNγ response gene, and serves as a useful marker for response against influenza." (PMID 31461941, 2019). "Natural Killer (NK) cell-mediated early innate defense responses to influenza infection include the killing of infected epithelial cells and generation of anti-viral cytokines including interferon gamma (IFN-γ)." (PMID 30899058, 2019). "The post vaccination expansions of influenza-specific IFNg-producing T-helper cells as measured by Elispot were shown to tightly correlate with increase of neutralizing antibodies." (PMID 31019503, 2019). "As major contributors of IFNγ, a crucial cytokine in the anti-influenza armamentarium, ILC1s induce cytolysis of IAV-infected cells." (PMID 31612153, 2019). "Further, we found that IFNγ suppresses PPARγ expression during influenza and influenza-MRSA super-infection in mice." (PMID 31159430, 2019). "Next, our results showed that rosiglitazone treatment decreased the expression of IFNγ during influenza infection." (PMID 31159430, 2019). "These peptides were synthesized, assembled into a peptide matrix and were incubated with BAL cells from a swine influenza infected pig ex vivo and IFNγ release was measured by ELISpot." (PMID 29772011, 2018). "We found increased levels of IFNγ and IFNγ-induced ISGs in Stat2−/− mice during influenza-bacterial super-infection." (PMID 30337919, 2018). "We treated both influenza-infected WT and Stat2−/− mice with anti-IFNγ, followed by super-infection with MRSA, and measured subsequent bacterial burden." (PMID 30337919, 2018). "Later infection of MRSA after influenza however, exacerbates bacterial replication due to inhibition of IL-13 and an upregulation of IFNγ." (PMID 30619303, 2018). "We found that improved bacterial control seen during influenza-bacterial super-infection in Stat2−/− mice was lost upon neutralization of IFNγ." (PMID 30337919, 2018). "Studies have shown that influenza-induced IFNγ inhibits pneumococcal control during super-infection." (PMID 30337919, 2018). "We found an increase in the levels of the inflammatory cytokines IL-1α, IL-1β, TNFα, IL-6, IL-12p40, IL-17, and IFNγ, and increased levels of the Type 2 cytokines IL-4 and IL-5, in influenza-infected Stat2−/− mice when compared to WT mice." (PMID 30337919, 2018).
influenza (continued). "This increase in annotations and genes for response to interferon-gamma is likely driven by research preference, as it coincided with increased research interest in influenza infection following the 2009 H1N1 influenza pandemic." (PMID 29572502, 2018). "BALB/c mice respond to an acute influenza insult via IFNγ dependent alveolar macrophage depletion, whereas C57BL/6 mice do not." (PMID 30619303, 2018). "The role of IFNγ in suppression of memory CD8+ T-cells has been reported in lung following influenza infection." (PMID 29170671, 2017). "Co-administration of IL12 and influenza subunit vaccine to newborn mice led to increased splenic expression of IFNγ, IL10 and IL15 mRNA and enhanced protective efficacy of antiviral immunisation." (PMID 29124321, 2017). "Our results are in accordance with previous report showing increased IFNγ+ NK cell frequencies in pregnant women following influenza infection or vaccination." (PMID 29145441, 2017). "The GPI-0100 dose was negatively correlated with the number of influenza-specific IFNγ- and IL17-producing T cells and positively correlated with the number of IL4-producing T cells observed after immunization and challenge." (PMID 28749414, 2017). "In mice, CD4 effectors of multiple subsets including helper type 1 (Th1) cells producing interleukin-2 (IL-2) and IFNγ that recruit virus-specific cytotoxic T lymphocytes (CTL) to the lungs to kill influenza-infected lung epithelial cells." (PMID 26941738, 2016). "We observed that while production of both IFNγ and IL-10 in whole PBMCs declined with age, the IFNγ:IL-10 ratio declined, suggesting a possible shift toward a more anti-inflammatory response to influenza." (PMID 27322555, 2016). "NK cells are crucial for innate immune responses against viruses such as influenza, via cytokine release (especially interferon gamma (IFN-γ)) and cytotoxicity towards infected target cells." (PMID 26820305, 2016). "We have shown that older people who develop influenza illness have low levels of the cytolytic mediator, granzyme B (GrB), and a lower ratio of IFNγ:IL-10 released from peripheral blood mononuclear cells (PBMC) following challenge with live influenza virus." (PMID 27322555, 2016). "The frequency of influenza-specific IFNγ-secreting cells in peripheral blood was measured using an IFNγ ELISpot assay." (PMID 27311020, 2016). "Increases in IL-6 and IFNγ have also been observed in nasopharyngeal lavage samples taken from influenza patients, BAL samples taken from flu infected rhesus macaques and BAL samples from rhesus macaques infected with pulmonary nontuberculous mycobacteria." (PMID 27677639, 2016). "Influenza A virus infection predominantly induces a Th1 response, with most CD4 effectors producing IFNγ though the importance of IFNγ in combating the flu has been debated." (PMID 27148257, 2016). "Although we were unable to detect IFNγ in our BAL samples we have recently demonstrated an excess production of IFNy by COPD-derived T cells in an influenza infection model in the context of aberrant exhaustion signalling." (PMID 27898728, 2016). "Resistance to infection was independent of adaptive immune responses, including the expansion of specific IFNγ secreting cells or production of influenza-specific antibody." (PMID 27279280, 2016). "Three of the four F9-NpM1 vaccinated birds challenged with influenza showed IFNγ responses that distinguished them from F9 vaccinated and challenged birds (40.0 ± 12.5 vs. 3.0 ± 1.9, p < 0.05)." (PMID 25450002, 2015). "In our current study, we observed increased IFNγ protein levels in the influenza-infected IL-27Rα−/− mice compared to WT, confirming that IL-27 signaling attenuates IFNγ production during influenza infection." (PMID 25651926, 2015). "Our results are the first to demonstrate detection by flow cytometry of influenza-specific IFNγ responses in individual T cells from LPAI infected birds." (PMID 25450002, 2015).